FOXP3 (forkhead box P3)
Diseases named in the same sentence as FOXP3 in open-access papers (continued):
Sharing a sentence is not in itself a finding about the gene and the disease.
infection (continued). "Together, these findings suggest that Foxp3+ Tregs, like effector CD4+ T cell subsets, respond to local cytokines by modifying their chemokine receptors including CXCR3 to promote their migration to sites of inflammation and infection where they function to suppress immune responses." (PMID 30915078, 2019). "The percentages of CD4+ CD25+ FoxP3+ T-reg cells increased from 21% in noninoculated middle ear fluid to 70% in day 3 and day 7 NTHi-infected middle ear fluid, confirming the induction of T-reg cells by sustained NTHi infection." (PMID 31548315, 2019). "Moreover, microarray assay in combination with CRNG interference and overexpression showed that the differential genes such as ANPEP, KITLG, STAT5A, FOXP3, miR-451, IL-2, IL-10, IL-6, and TNF-α are mainly involved in viral and pathogens infection and the immune-inflammatory responses in PK-15 cells." (PMID 31178726, 2019). "Data indicated that CRNG significantly increase KITLG, FOXP3 and miR-451, and decrease ANPEP and STAT5A mRNA expression, suggesting that CRNG may be necessary for the modulation of antiviral immunity, inflammation and pathogen infection." (PMID 31178726, 2019). "Interestingly, a significantly greater percentage of Foxp3+ Tregs from naïve B6 mice migrated to CXCR3 ligands than cells from infected mice, suggesting the possibility that expression of CXCR3 on Tregs is down-regulated during infection." (PMID 30915078, 2019). "Therefore, a reduction in the influx of CD4+Foxp3+ cells at 30 days of infection does not play an evident role in controlling pathogen replication or the lung inflammatory response." (PMID 30584243, 2018). "At 6 days post-infection, when the L4 stage had almost completely attenuated the clinical severity and pathological signs of EAE, CD25+ cell numbers expanded significantly, with parallel growth of CD8+ and CD4+, both CD25+Foxp3+ and CD25+Foxp3− subsets and alternatively activated macrophages." (PMID 28975357, 2018). "Upon infection, Foxp3 has been reported to inhibit HIV transcription through inhibition of nuclear factor of activated T-cells (NFAT) and nuclear factor (NF)-κB activation in vitro, whereas other studies suggest that Foxp3 enhances HIV gene expression via the NF–κB signaling pathway." (PMID 29710792, 2018). "The expression of Foxp3 and IL17a was not changed 7 days after infection in both groups." (PMID 29033934, 2017). "Therefore, it is possible that CD39+ Foxp3+ Tregs could control HIV infection, especially during the first days of infection, prior to the HIV dissemination to the secondary lymphoid organs, phase where just a few effector T cells are activated." (PMID 27242797, 2016). "Within the CD4 SP population, and beyond the increased basal death levels of Foxp3+ compared to Foxp3− cells, the latter population showed a significant increase in annexin V staining after infection; this not being the case among Foxp3+ cells in which such staining was visibly diminished." (PMID 26745276, 2016). "CCR5-dependent recruitment of CD4+Foxp3+ Tregs may dictate the magnitude of the CD4+ Th1 and/or Th17 subset responses to favor a detrimental or beneficial effect on pathogen persistence at the site of infection." (PMID 27439902, 2016). "However, when Treg cells were pre-treated with the 2G-S24P and 2G-S16 anionic dendrimers at 10 μM, the percentage of the expression Foxp3 level was similar to non-infected Treg after 5 days of X4-HIV-1NL4.3 infection." (PMID 26785250, 2016). "We show that infection of mice with the chronic gastrointestinal helminth Heligmosomoides polygyrus drives rapid polyclonal expansion of Foxp3+Helios+CD4+ thymic (t)Tregs in the lamina propria and mesenteric lymph nodes while Foxp3+Helios−CD4+ peripheral (p)Treg expand more slowly." (PMID 26286232, 2016). "Furthermore, infection failed to induce Foxp3+ Treg cells to produce the suppressive cytokine interleukin 10 (IL-10)." (PMID 26195548, 2015).
infection (continued). "However, we found that S. mansoni larvae do not induce a Foxp3+ Treg cell response during the early stage of infection in C57BL/6 mice." (PMID 26195548, 2015). "Previous infections did not increase the number of Foxp3+ cells in either the spleen or the CNS." (PMID 24401094, 2014). "Thus, to determine whether Treg depletion after infection influences bacterial burden, we made use of DEREG mice that allow the specific depletion of FoxP3+CD4+ Tregs cells by administering DT." (PMID 25050936, 2014). "To address this, we depleted Tregs after infection with M. bovis BCG or Mycobacterium tuberculosis (Mtb) using DEREG mice, which express the diphtheria toxin (DT) receptor under the control of the FoxP3 locus, thereby allowing the selective depletion of FoxP3+ Tregs." (PMID 25050936, 2014). "However, while CD4+Foxp3+ Tregs that were adoptively transferred 2 days prior to JEV infection made the recipients vulnerable to JE, CD4+Foxp3+ Tregs that were adoptively transferred 2 days after infection provided resistance to JE (unpublished personal data)." (PMID 25188232, 2014). "However, when Foxp3+ Tregs were depleted before and during the course of infection no protection from infection was observed." (PMID 24098124, 2013). "This indicates that H. polygyrus primarily induces an adaptive Foxp3+ Treg-cell response at the infection site, bearing in mind that the use of Helios as a natural Foxp3+ Treg-cell marker may not be accurate in all immune contexts 48–50." (PMID 23319295, 2013). "Moreover, a subset of CD14+ cells with low HLA-DR expression have recently been reclassified as myeloid-derived suppressor cells, and expand during infection or inflammation where they are capable of suppressing T cell responses and induce CD4+ CD25+ Foxp3+ regulatory T cells." (PMID 23446058, 2013). "Infection with H. polygyrus did not change the percentage of MLN CD4+Foxp3+ Treg cells in either WT or ICOS−/− mice, indicating that ICOS deficiency impaired the expansion of CD4+Foxp3+ Treg cells and CD4+Foxp3− Teff cells to a similar extent." (PMID 23319295, 2013). "In our studies, Foxp3+ cells isolated from L. major infected tissue did not up-regulate T-bet, which may be explained by different infections, different stages of infection or different tissues studied." (PMID 23825948, 2013). "However, none of the recovered donor CD4 T cells were positive for GFP in either NOD or NODTGFβ recipients indicating that infection in the local presence of TGF-β does not induce Foxp3 expression in CD4 T cells." (PMID 22355341, 2012). "Forkhead box P3 (FoxP3) expression was not altered by either S. flexneri infection or by PETIM-DG treatment while transforming growth factor-β (TGF-β) expression increased 2.3-fold upon infection and was not altered by PETIM-DG treatment." (PMID 22887873, 2012). "Furthermore, while the number of CD4+Foxp3− T cells was similar between the groups on day 8 post infection (data not depicted), CD8+ effector T cells were elevated in the lungs of IL-10−/− mice." (PMID 22393401, 2012). "In addition, the absolute numbers of CD25+FoxP3+ T cells was not different between the two groups until day 8 post-infection when the numbers in infected BALB/c mice were higher (although not significant) than in the C57BL/6 mice." (PMID 22860150, 2012). "Furthermore, the frequencies of CD4+CD25+Foxp3+ Treg cells in the mLN and LP were comparable between WT and CD103−/− mice, both preceding and following infection." (PMID 21573179, 2011). "Also, CXCL-10 is specific for effector T-cell recruitment during infection and, therefore, its deletion reduces T-cell trafficking, which enhances production of CD4+CD25+Foxp3+ and suppressive cytokines interleukin-10 (IL-10) and tumor growth factor- β1 (TGF-β1)." (PMID 21439091, 2011).
infection (continued). "However this contrasts with other studies, which reported a minor increase in Foxp3 expression during P. berghei infection at Day 7 post-infection (early expression of Foxp3 was not reported in this article)." (PMID 21439091, 2011). "We show here, that following its natural route of infection, wild-type MV induces a strong and broad activation of the immune system, the generation of MV-specific humoral and cellular anti-viral responses, accompanied by an increase in the frequency of regulatory CD4+CD25+Foxp3+ T cells." (PMID 19319188, 2009). "Furthermore, adoptive transfer of CD25+ and/or CD25− CD4+ T cells into RAG−/− mice also failed to reveal any role for CD25+ Foxp3+ cells in this infection." (PMID 18401464, 2008). "Here we have examined the role of natural and adaptive regulatory T cells in the control of malaria infection and find that classical CD4+CD25hi (and Foxp3+) regulatory T cells do not significantly influence the outcome of infections with the lethal (17XL) strain of Plasmodium yoelii (PyL)." (PMID 18401464, 2008). "However, at 72 hours post-infection, the expression of IL-17, IFN-γ, T-bet, RORγt, and IL-6 genes was markedly reduced in the Pm_OMVs-infected group compared to the Pm group (P < 0.01), whereas the expression levels of TGF-β, GATA-3, IL-4, and FoxP3 were significantly increased (P < 0.01)." (PMID 41306977, 2025). "Antibody treatment of RelBΔDC mice did not completely deplete Foxp3+ Treg cells in the peripheral blood but rather temporarily reduced their frequency to control levels during the primary infection and increased again after finishing the treatment at day 28 post primary infection." (PMID 39443450, 2024). "Foxp3 was highly expressed in both T5 and T9 populations, similar to Treg cells; therefore, we reclustered 1,313 cells derived from clusters T5 and T9 to further investigate the mechanisms of negative immune regulation in mice after infection with E. granulosus." (PMID 37039643, 2023). "However, how these responses related to FoxP3+ Tfh cells in the periphery is unclear, and here the proportion of FoxP3+ Tfh cells was not modified by age, current infection, or household mosquito exposure, but there was a trend to higher FoxP3+ Tfh cells in males." (PMID 35851033, 2022). "Furthermore, at 2 wk postinfection, the number of CD4+CD25+FoxP3+ Treg cells was significantly lower in the lungs of CSE−/− mice, which was reversed at 4 wk postinfection, suggesting control of the proinflammatory immune response in the CSE−/− mice after 4 wk of infection." (PMID 32139610, 2020). "Interestingly, when the HLN from the same study was examined, there was little evidence of expansion of the CD4 Foxp3 population with no significant changes in sheep with only goats showing a ~6% increase over baseline during the acute infection stages localized to the cortex." (PMID 28871261, 2017). "However, we do not rule out a role for FoxP3+ Treg cells in the control of RSV pathology, as we have observed an increase in Treg cells in the airways after AvCystatin treatment during primary infection and previous work has implicated a role for Treg cells in suppressing RSV immunopathology." (PMID 27560829, 2016). "Thus, while it is likely that the lack of Foxp3+ Treg cell activity in early S. mansoni infection is a general feature of infection, there remains the possibility that in other, as yet untested strains, Foxp3+ Treg cell activation and expansion may occur." (PMID 26195548, 2015). "Given that WT, but not TLR-9-/- mice exhibited increased numbers of ileal FOXP3+ cells upon infection, reduced Treg numbers might be indicative for compromised ileal mucosal regulatory properties in the absence of TLR-9, which in turn contributes to a more devastating inflammatory scenario." (PMID 24932221, 2014).
infection (continued). "Regulatory T cells might suppress strong virus-specific CD8+ T cell responses, but this appears unlikely because there is no significant change in CD4+CD25+FoxP3+ T cell frequency following infection, and primary LCMV-specific CD8+ T cells response were unabated in CVB3-infected animals." (PMID 19834548, 2009). "Expansion of Foxp3-GFP+ cells was observed in mice challenged with heat-killed parasites, with many found robustly migrating within the primary infection site (visualized by the lack of blue collagen structures)." (PMID 38114497, 2023). "Interestingly in C57BL/6 mice, S. japonicum infection dynamically impacts Foxp3 expression in T cells, with no significant change 4 weeks after infection, but with a significant increase and decrease in Foxp3 expression at 6 and 8 weeks after infection, respectively." (PMID 35666747, 2022). "FOXP3+ cells expressing T-bet and ROR-γt have also been shown to have little or no suppressive activity in tissue niches in infection and in tumors." (PMID 35821823, 2022). "Following infection, there is a shift towards lower pro-inflammatory reaction by higher levels of IL10 and TGFβ, and an increase in FoxP3 negative Treg co-expressing IL10, IFNγ, and TNF." (PMID 34684226, 2021). "Meanwhile, no change was observed in the frequency of CD4+FoxP3+ T-cells in the blood and spleen of HIS-NSG mice after 30 days or 60 days of infection, except an increase in MLN." (PMID 34685494, 2021). "Frequencies of Foxp3+ Treg within the CD4+ T cell population were similar in the small intestine of both mouse lines and did not change during infection in BALB/c and C57BL/6 mice." (PMID 31889073, 2019). "A negative correlation confirmed that as more CD4+ cells, lesser CD4+Foxp3+ cells in the lungs of CCR4−/− mice, but not WT mice, at 70 days of infection." (PMID 30584243, 2018). "The overall frequencies of Foxp3+ Treg were similar in mLN of naive SPF and GF mice and did not change significantly upon infection." (PMID 30349532, 2018). "We did not observe any differences in the frequencies of Foxp3+ Tregs among CD4+ T cells during long-term depletion of DC in P. yoelii-infected mice, whereas starting depletion at day 4 of infection resulted in decreased percentages of Tregs." (PMID 29085373, 2017). "The downregulation of Foxp3 in X4-HIV-1NL4.3 infected Treg cells was detected at day 3 (data not shown) and day 5 post-infection." (PMID 26785250, 2016). "On the other hand, adoptive transfer of CD4+ Foxp3+ T cells from mice stimulated with T. cruzi-exposed BMDC was able to reproduce the suppression of OTI CD8+ T cell priming in vivo, in absence of infection." (PMID 27332899, 2016). "In contrast, infection with SS1 strain, which lacks a functional T4SS, failed to upregulate IL-10 production and FoxP3 expression." (PMID 25807464, 2015). "In consideration of this close connection of Th17 cells and Tregs and the complexity of the cytokine environment during infection it is not surprising that naïve, TGF-β-activated T cells can co-express RORγt and Foxp3." (PMID 26635744, 2015). "As Foxp3+ Treg depletion is not permanent in DEREG mice, we investigated the effect of transient Foxp3+ Treg depletion either during initial infection or during vaccination of chronically infected mice." (PMID 25255463, 2014). "Within H. polygyrus-infected WT mice the CD4+Foxp3− Teff-cell population expanded at a slower rate than the CD4+Foxp3+ Treg cells, not increasing significantly until day 14 of infection." (PMID 23319295, 2013). "Flow cytometric analysis of Foxp3+CD4+ cells at 6 and 10 weeks post-infection indicated that the transfer of WT Tregs did not increase the frequency of this population in the lungs of TLR2KO mice, which were significantly lower than WT controls at 6 weeks." (PMID 23785280, 2013).
infection (continued). "Adaptive type 1 regulatory (Tr1) CD4+ cells, which do not express CD25, FoxP3 or CD127 on their surface, have recently been identified as the main source of IL-10 in experimental murine infection with P. yoelii." (PMID 22973442, 2012). "Although the number increases due to infection, developmental exposure to BPA did not alter the number of CD4+ T cells, including those phenotypically defined as regulatory T cells (CD3+CD4+CD25+FoxP3+) in the MLN or lung on days 7 or 9 p.i.." (PMID 22675563, 2012). "Conversely, we demonstrate that populations of adaptive regulatory CD4+ T cells, that are CD25−, Foxp3− and CD127−, and which do not make IFN-γ, IL-4 or IL-17, develop during both PyL and PyNL infections." (PMID 18401464, 2008). "In accordance with the prominent CD103+ALDH+ DC population detected in MLN, BALB/c displayed a significant rise of Treg frequencies at day 6 post-infection, whereas CD4+ T cells of C57BL/6 mice comprised similar proportions of Foxp3+ T cells irrespective of the infection status." (PMID 39910093, 2025). "Interestingly, we observed differential Treg responses, wherein classical CD4+ Tregs were either not induced during infection or induced in both Ascaris and coinfected pigs, contrasting with a rise in CD8+FoxP3+ Treg seen only in Ascaris-infected pigs." (PMID 39140728, 2024). "By comparing sublethal with lethal dose infection in vivo, we found that not the viral load but an increased number of CD4+/CD25+FoxP3+ Tregs may impair the immune response by suppressing virus specific CD8+ T cells and favors disease progression." (PMID 38979428, 2024). "This was only the case for rTregs, aTregs, and FoxP3+/CD4+ Tregs (not naive or memory populations), which could suggest a reduction in the blood counts of functionally active Tregs at the time of infection." (PMID 35406717, 2022). "In line with our previous data infection of BALB/c mice with S. ratti did not alter the frequency of conventional Treg, defined as Foxp3+ T cells within the CD4+ T cells, while the frequency of Foxp3+ cells increased in infected F1 and C57BL/6 mice compared to non-infected mice." (PMID 33452272, 2021). "Other immunoregulatory markers such as IL-21, FoxP3 and TGF-β showed no significant expression variations between vaccinated and infected control group (group C) although a tendency of being dysregulated during infection was detected." (PMID 32517744, 2020). "These cytokine levels, in combination with a lack of Foxp3 induction on CD4+CD25+ T cells, indicated that H. polygyrus induced a regulatory immune response in the EAE mice, which has been previously reported for H. polygyrus single infection." (PMID 28975357, 2018). "Furthermore, Foxp3+ Treg cells at these sites did not exhibit an increase in activation status in response to infection, as their expression levels of CD25, Foxp3, and Helios remained constant." (PMID 26195548, 2015). "In a first step, we tested if infection with retroviruses, which overexpress phosphorylation-independent and thus constitutively active (CA) forms of STAT5 or FOXO1, might rescue FOXP3 expression in the presence of the TCR-signal and absence of TGFβ." (PMID 26815406, 2015). "Notably, NNH with progressive infections have higher levels of CTLA-4, Foxp3, and IDO mRNA in their lymphoid tissues compared to non-progressors and uninfected individuals." (PMID 24732038, 2014). "Protection from infection was dependent on CD4+ T-cells, but appeared independent of Foxp3+ Tregs." (PMID 24098124, 2013). "Maintenance of relatively higher expression levels of TGF-β in the chronic phase of the infection in aly/aly mice may be related to the generation and maintenance of CD4+Foxp3+ Tregs rather than the inhibition of granuloma maturation." (PMID 22928057, 2012).